MIR217 (microRNA 217)
Synonyms: hsa-mir-217; miR-217; MIRN217
Gene: MicroRNA gene on chromosome 2 (55,982,967 to 55,983,076, reverse strand). Ensembl gene ENSG00000207548.
Gene Ontology:
Biological process: miRNA-mediated post-transcriptional gene silencing
Cellular component: RISC complex
Homologues: Orthologues: chimpanzee ptr-mir-217 (100% identical), macaque mml-mir-217 (92% identical), guinea pig MIR217 (89% identical), pig ssc-mir-217-1 (87% identical), rat Mir217 (82% identical), dog MIR217 (73% identical), zebrafish mir217-1 (68% identical), tropical clawed frog xtr-mir-217 (64% identical), rabbit MIR217 (55% identical).
Diseases named in the same sentence as MIR217 in open-access papers:
MIR217 is named in the same sentence as 1 disease in open-access papers, as found by Europe PMC text mining. Sharing a sentence is not in itself a finding about the gene and the disease. The quoted sentences say what the papers report.
cancer (1 paper, 2023). A tumor composed of atypical neoplastic, often pleomorphic cells that invade other tissues. "Serpin family I member 2 (SERPINI2), a tumor suppressor gene downregulated in PDAC and other cancers, and microRNA mir-217 (MIR217), a potential tumor suppressor gene in PDAC, which targets KRAS expression, were among the most underexpressed genes in the OCM tumors." (PMID 36579622, 2023).